RN7SL561P (RNA, 7SL, cytoplasmic 561, pseudogene)
Gene: Miscellaneous RNA gene on chromosome 20 (1,666,360 to 1,666,640, forward strand). Ensembl gene ENSG00000242348.
Homologues: Orthologues: macaque Metazoa_SRP (86% identical). Paralogues in human: RN7SL1 (81% identical), RN7SL2 (81% identical), RN7SL665P (81% identical), RN7SL45P (80% identical), RN7SL709P (80% identical), RN7SL3 (80% identical), RN7SL127P (79% identical), RN7SL493P (79% identical), RN7SL856P (79% identical), RN7SL126P (78% identical), RN7SL357P (78% identical), RN7SL416P (78% identical), and 703 more.